IL15 (interleukin 15)
Diseases named in the same sentence as IL15 in open-access papers (continued):
Sharing a sentence is not in itself a finding about the gene and the disease.
tumor (continued). "Additionally, the observed reduction in tumor growth was driven primarily by NK cells and not CD8 T cells, which corresponds to the enhanced NK cell development, maturation, and function in NSG‐Tg(Hu‐IL15) mice." (PMID 35959876, 2022). "Moreover, the 60 s kINPen plasma treatment, which reduced absolute lesion and tumor sizes significantly, was the only treatment not showing a reduction in ACVR1B, ACVR2A, CSF1, EGF, EGFR, IL15, and IL6RA when compared to all other treatments in the high dose DBP group." (PMID 34667240, 2021). "We could not observe tumor growth advantage in B16F10-bearing C57BL/6 mice with murine IL-15 treatment; it likely due to the expansion and activation of CD8+ T cells upon murine IL-15 treatment." (PMID 29255466, 2017). "IL-15 or its agonists have not been shown to play a direct role in regulating MDSC expansion or activity, thus it is anticipated that ALT-803 therapy may only have marginal effect in the population of MDSCs in tumor infiltrates." (PMID 26625316, 2016). "The anti-tumor activity might be improved by introducing a CD16 transgene, similar to the FT596—the first iPSC-derived CAR-NK cell product that underwent a clinical trial (NCT04245722)—which expressed a high-affinity, non-cleavable CD16 with an IL-15 receptor fusion protein (IL-15/R-hnCD16)." (PMID 37445684, 2023). "Furthermore, we found that IL-15 could induce human CD4+ T cells to develop memory phenotypes more easily than human CD8+ T cells, the induced memory CD4+ T cells could respond to DCs pulsed with tumor antigens (Data not shown)." (PMID 32221812, 2020).
cancer (461 papers, 1999 to 2026). A tumor composed of atypical neoplastic, often pleomorphic cells that invade other tissues. "Survival analyses conducted using database resources have revealed an association between IL-15 expression and favorable cancer prognosis across multiple cancer types (pan-cancer)." (PMID 39911393, 2025). "In humans, acute bouts of exercise mainly high intensity, has elicited significant increases in systemic IL-15 and other myokines (e.g., IL-6, oncostatin-m) that have been implicated in the suppression of cancer growth in pre-clinical and in-vitro models." (PMID 41350482, 2025). "We investigated the biological function of cancer cell-intrinsic IL-15 and its underlying mechanism." (PMID 38637902, 2024). "Previously, only a few small studies had examined the association between the clinical outcome in patients with cancer and the level of IL-15 or its receptors (IL-15R)." (PMID 36831406, 2023). "On the other hand, with the higher production of granzyme B of NK cells in the IL-15 mDCs (6 days group), associated with enhance cytotoxicity with CD107a degranulation assay against K562 cancer cells compared to other groups." (PMID 35413499, 2022). "Recently, strategies for cancer treatment using IL-15 alone or associated with other therapies have been reported." (PMID 35919494, 2022). "Next, the TIMER database was used to further evaluate the relationship between immune-associated cells infiltration and IL-15 expression in pan-cancer." (PMID 36467072, 2022). "First of all, the relationship between IL-15 expression and immune-associated cells infiltration in pan-cancer was assessed using the ssGSEA algorithm." (PMID 36467072, 2022). "Meanwhile, potential relationships between IL-15 mRNA expression levels and clinical features, DNA gene mutations, immune cells infiltration, and pathway regulation were evaluated in pan-cancer." (PMID 36467072, 2022). "But currently, rare studies have discovered the association between IL-15 and ferroptosis/cuproptosis-related genes in pan-cancers, which is wealthy to explore." (PMID 36467072, 2022). "Decreased IL-15 caused by low skeletal muscle reduces the number and activity of natural killer cells and worsens the prognosis of cancer patients." (PMID 33915929, 2021). "These properties result in a reduced risk of toxicity related to cytokine spikes, making the IL-15:IL-15Rα complex the most favorable form for cancer immunotherapy in humans." (PMID 33671252, 2021). "An NDV variant encoding both IL-15 and IL-7 developed as a cancer vaccine conferred delayed outgrowth of B16 tumors." (PMID 31623390, 2019). "Several reports have demonstrated that IL-15 gene polymorphisms were significantly related to cancer risk and overall survival." (PMID 29162948, 2017). "Mammary carcinogenesis and efficacy of cancer immunoprevention, and immune mechanisms, were studied in IL15-deficient and IL15-proficient NeuT mice." (PMID 25997501, 2015). "A fusion between Pembrolizumab and IL-15 cytokine is deemed as a prominent anti-cancer molecule since Pembrolizumab mAb has shown clinical success in treating various cancers and a number of pre-clinical studies has underlined immunostimulatory effects of IL-15 cytokine." (PMID 39808627, 2025). "This approach also directly boosts the killing ability of CAR-NK cells through the localized production of specific cytokines (e.g., IL-15), allowing them to eliminate cancer cells and cancer-associated fibroblasts, disrupt solid tumor structures and enhance therapeutic effects." (PMID 40705122, 2025). "Further, treatment-induced ADA may have an adverse effect on endogenous wild-type IL-15 and cause physiological dysfunctions that may impact cancer development." (PMID 39965362, 2025).
cancer (continued). "Overexpression or downregulation of certain EPH receptors has been shown to be associated with tumorigenesis in some types of cancers.20) IL15 is a cytokine that promotes the activation of NK and CD8+ T cells, which play a central role in regulating the immune system." (PMID 40678018, 2025). "Furthermore, the expression of IL-15 was correlated to the infiltration levels of various immune-associated cells in pan-cancer assessed by the ESTIMATE algorithm and TIMER database." (PMID 36467072, 2022). "In addition, studies have shown that CSCs from various cancer types are susceptible to IL15-activated NK cells and this targeting was associated with increased expression of NK ligands on the surface of CSCs." (PMID 35765577, 2021). "Bearing this in mind, IL-15 could be used as an early marker to highlight high-risk patients and the subsequent adjustment of the cancer therapy strategy." (PMID 32929618, 2021). "The delivery of genes encoding a soluble receptor α along with IL-15 could improve the efficacy of this anti-cancer immune therapy." (PMID 33096755, 2020). "However, there are other reports indicating that IL-15 is associated with cell proliferation in several cancers." (PMID 29255466, 2017). "Our group has developed IL-15 TriKEs targeting singular cancer-associated markers." (PMID 27650544, 2016). "In cocultures, IL-15 T cell activation significantly reduced cancer population growth of ribociclib sensitive and resistant cells." (PMID 40032842, 2025). "Interleukin‐15 (IL‐15) is a pleiotropic cytokine recognized as a promising therapeutic agent in cancer immunotherapy." (PMID 40799128, 2025). "Recent preclinical and clinical studies suggest that IL-15 can be used to improve the efficacy of immunotherapies, particularly in cancers where TRM cells play a central role in local immunity." (PMID 40066439, 2025). "The resulting IL-15 production minimizes exhaustion and enables NK cells to replenish their granules, facilitating multiple serial killing events against cancer cells." (PMID 40646591, 2025). "A study investigated how quercetin influences cellular immunity against cancer by examining IL15 expression and its regulatory mechanisms." (PMID 40880749, 2025). "Several clinical trials involving patients with malignancies have demonstrated that the potential efficacy of systemically administered NK cells that have been genetically modified to express IL-15 and a CAR." (PMID 40176196, 2025). "IL-15 confers anti-cancer function by stimulating immune response CD8+ T cells and natural killer (NK) cells against cancer cells." (PMID 40863244, 2025). "We confirmed, using cancer-macrophages-T cell tricultures, that in presence of monocyte derived macrophages the combination of ribociclib and IL-15 promotes cancer control via T cell killing." (PMID 40032842, 2025). "As a result, cancer patients exhibiting weakened immune systems who receive adoptively transferred NK or T cell therapies frequently lack sufficient intrinsic IL-15 support, restricting the persistence and activation of therapeutic cells." (PMID 41455698, 2025). "IL-15 is a cytokine with significant potential in cell engineering, immunotherapy, and cancer therapy." (PMID 41523590, 2025). "TriKE (tri-specific killer cell engager) is a class of trispecific fbab, targeting NK cell antigen CD16, cancer/viral antigen, and includes tandemly linked scFv or VHH with an inserted IL-15 (interleukin-15) domain to stimulate NK cells." (PMID 40700292, 2025). "Cytokines from the common gamma chain receptor family, such as IL-15, IL-21 and IL-7, show promise for cancer immunotherapy and have been incorporated individually into the immunocytokine approach." (PMID 40370435, 2025). "Currently, several IL-15-delivering platforms are in preclinical and clinical development for cancer treatment—each with variations in IL-15 conformation that confer increased stability, bioavailability, and in vivo half-life." (PMID 41373645, 2025).
cancer (continued). "Recently, IL-15 has attracted considerable attention in cancer immunotherapy due to its significant immunomodulatory effects." (PMID 41455698, 2025). "The findings suggest that quercetin inhibits cancer cell proliferation by downregulating IL15 expression through increased promoter methylation." (PMID 40880749, 2025). "CD8 + T cell activation was confirmed by Interferon gamma (IFN-γ) production in monoculture p (<0.05) and coculture with cancer cells when treated with IL-15 (p < 0.0001)." (PMID 40032842, 2025). "TriKE is a class of trispecific fbab, with a first domain targeting the NK cell antigen CD16, second cancer or viral antigen, and a third domain composed of an inserted IL-15 fragment to stimulate NK cells." (PMID 40700292, 2025). "The IL15‐displaying nanovesicle introduced here holds promise as a potential platform for immunochemotherapy in the treatment of cancer." (PMID 39625860, 2025). "For each cancer cell line, we then compared the impact of IL-15 treatment on cancer growth in cancer monocultures and cancer-T cell co-cultures between ribociclib treatment and DMSO control conditions." (PMID 40032842, 2025). "In this work, we propose a co-hitchhiking strategy for delivering PhA and recombinant IL-15 (rIL-15) via an engineered recombinant protein consisting of the IL-15Rα-sushi domain fused with the Fc domain of IgG to enhance cancer photoimmunotherapy." (PMID 40430906, 2025). "Our analyses identified that shrinking ribociclib-sensitive tumors had increased IL-15 signaling between macrophages, T cells and cancer cells, leading to increased T cell activation and stronger antigenic interferon responses." (PMID 40032842, 2025). "IL-18 contributes to NK cell activation by upregulating the expression of perforin and granzymes, and when used in conjunction with IL-12 or IL-15, it can significantly boost NK cell-mediated cytotoxicity against various cancer cell lines." (PMID 40255394, 2025). "In vitro cancer-immune coculture assays showed that IL-15 treatment can reinvigorate T cell proliferation and cancer control." (PMID 40032842, 2025). "Further, the immune suppressive effect of ribociclib on T cells opposed IL-15 T cell activation, reducing the efficacy of T cells in regulating cancer growth." (PMID 40032842, 2025). "Among these cytokines, IL-15, an essential cytokine for NK cell proliferation and activation, is being tested in clinical trials to enhance NK cell responses in older adults and cancer patients." (PMID 40255394, 2025). "Genetically engineered cells co-expressing IL-15/IL-15Rα complex for secretion is also emerging for cancer treatment." (PMID 38368374, 2024). "Combining IL-15 therapy with anti-cancer monoclonal antibodies (mAbs) has been shown to improve their antibody-dependent cellular cytotoxicity." (PMID 39507777, 2024). "Another TriKE, which contained a camelid anti-CD16 antibody fragment, a wild type IL-15, and an anti-B7-H3 scFv was tested in vitro in an array of cancer cell lines as well as in NSG mice grafted with MA-148 ovarian cancer cell line." (PMID 39294470, 2024). "The value of IL-15 immunotherapies in cancer is primarily related to their ability to expand lymphocyte populations." (PMID 38672094, 2024). "Immunotherapy has improved treatment outcomes for cancer patients, and ongoing efforts include a focus on harnessing the therapeutic potential of cytokines such as IL-2 and IL-15 in various cancer indications." (PMID 38887559, 2024). "The emergence of IL-15 immunotherapies for the treatment of cancer provides a range of therapeutic options for potential repurposing in NS." (PMID 38672094, 2024). "By amplifying the cytotoxic action of immune cells against tumors, IL-15 emerges as a promising candidate for cancer therapy, particularly in cancers known for immune evasion, such as HNC." (PMID 38672104, 2024).
cancer (continued). "The review presents an organized discussion of some immunomodulators, i.e., sulforaphane, sunitinib, sorafenib, dasatinib, metformin, and IL-23 and IL-15 aiding CAR T-cell therapy specifically in the mitigation of cancer." (PMID 39105978, 2024). "Another vital cytokine, IL-15 plays a crucial role in the stimulation of lymphocyte populations, and its potential to boost NK cell function presents new opportunities for cancer therapy." (PMID 38545115, 2024). "Subcutaneous injection or intravenous administration of IL-15 in metastatic malignant tumors promotes NK cell activation." (PMID 39263534, 2024). "This review focuses on ICKs designed with the most impactful cytokines in the cancer field: IL-2, TNFα, IL-10, IL-12, IL-15, IL-21, IFNγ, GM-CSF, and IFNα." (PMID 39204319, 2024). "Despite promoting cell migration via intracellular IL-15, a high level of IL-15 expression in cancer cells enhances the effector function of T cells and sensitizes tumors to anti-PD-L1 therapy." (PMID 38637902, 2024). "NK cells are instrumental in the innate immune defense against tumors, and their stimulation by IL-15 facilitates the direct targeting and elimination of cancer cells." (PMID 38672104, 2024). "Despite more work has to be done for developing a feasible IL-15-based therapy against cancer 156-157, the demonstrated interplay with physical activity should encourage further studies within this area of anticancer research." (PMID 38164270, 2024). "We previously reported the expression of an IL15-FlaB conjugate secreted from S. typhimurium for the treatment of cancer." (PMID 38323311, 2024). "Cancer cell-intrinsic IL-15 promoted cell motility and migration in vitro and metastasis in vivo via activation of the AKT-mTORC1 pathway; however, exogenous IL-15 inhibited cell motility and migration via suppression of the RhoA-MLC2 axis." (PMID 38637902, 2024). "To understand how intrinsic IL-15 affects the migration and invasion of cancer cells, we first investigated the signaling cascades mediated by intrinsic IL-15 in cancer cells." (PMID 38637902, 2024). "Our clinical study indicates that human CAR-NKTs benefit from the co-expression of the IL-15 cytokine to support their expansion and persistence in cancer patients." (PMID 38167707, 2024). "N-803 is an IL-15 receptor superagonist complex that has shown strong and broad anti-cancer effects in several murine cancer models, as well as enhanced tissue retention compared to soluble IL-15." (PMID 39401241, 2024). "Our data showed that cancer cell-intrinsic IL-15 promotes cell motility, migration, and invasion in vitro but does not alter cell proliferation." (PMID 38637902, 2024). "In line with this evidence, some studies are testing recombinant human IL-15 in cancer patients, including those with metastatic melanoma 89,90." (PMID 38164270, 2024). "IL-15 serves as a broad proinflammatory modulator and it holds promise for applications in cancer immunotherapy." (PMID 39447666, 2024). "Almost every aspect of NK cell immunity is regulated by IL-15, and so the value of this cytokine or its analogs in the treatment of various cancers are being investigated in several ongoing clinical trials." (PMID 39430751, 2024). "Further amplification in anti‐cancer efficacy was observed upon incorporation of the IL‐15 crosslinker." (PMID 39472273, 2024). "Provision of IL-15 within the TME likely involves CCR7+ DCs, which express high levels of IL-15 and IL-15RA, co-localize with NK cells in human cancers and can support further molecular interactions such as PVR:TIGIT55,71,72." (PMID 38267402, 2024). "IL-15 not only promotes the survival and proliferation of NK cells but also enhances their cytotoxic activity against cancer cells, making it a valuable component of adoptive cell therapy strategies." (PMID 39335671, 2024). "Next, we used loss- and gain-of-function approaches to assess the biological function of endogenous IL-15 in cancer cells." (PMID 38637902, 2024).